LEP (leptin)
Diseases named in the same sentence as LEP in open-access papers (continued):
Sharing a sentence is not in itself a finding about the gene and the disease.
endothelial dysfunction (continued). "Emerging biomarkers of endothelial dysfunction, including neopterin, osteoprotegerin, fetuin-A, homocysteine, leptin, adiponectin, PAI-1, CRP, IL-6, and CECs, provide additional understanding of the pathophysiology of endothelial damage." (PMID 40529825, 2025). "Although previous studies have examined the link between leptin and endothelial dysfunction, most relied on flow-mediated dilation or biochemical markers." (PMID 41470134, 2025). "Reductions in adiposity and leptin secretion lead to decreased endothelial leptin signaling, subsequently reducing NO bioavailability mediated by CCR5 and NADPH oxidase 1, directly causing ritonavir-associated endothelial dysfunction." (PMID 39311207, 2024). "Adipokines like chemerin and leptin are significantly elevated in PE and contribute to endothelial dysfunction and metabolic dysregulation." (PMID 39062815, 2024). "Leptin can increase oxidative stress, promote endothelial dysfunction, and increase arterial stiffness." (PMID 39062887, 2024). "An earlier study reported that leptin-mediated aldosterone secretion promotes endothelial dysfunction and the expression of pro-fibrotic markers in the heart, leading to cardiovascular disease." (PMID 38166618, 2024). "ObRb- and leptin-induced endothelial dysfunction have also been identified in the coronary arteries of various species particularly at high concentrations of the protein synonymous with hyperleptinemia." (PMID 38256208, 2024). "This inflammatory response can exacerbate HFpEF by promoting endothelial dysfunction and driving further myocardial damage, illustrating leptin’s dual role in both metabolic and cardiovascular inflammation." (PMID 39682585, 2024). "Leptin often exerts detrimental cardiovascular effects by promoting hypertrophy, fibrosis, and endothelial dysfunction." (PMID 39682585, 2024). "Leptin promotes myocardial hypertrophy, fibrosis, endothelial dysfunction, and inflammation, though contradictory evidence suggests potential cardioprotective roles in subgroups like obese African American women." (PMID 39682585, 2024). "To better understand the relationship between AR, PVAT, and endothelial dysfunction, we performed immunofluorescent localization of AR and leptin in the aortic wall with intact PVAT." (PMID 38132854, 2023). "In contrast, lifestyle interventions with increased omega-3s reduce insulin resistance, leptin concentrations, and endothelial dysfunction in obese adolescents." (PMID 37238961, 2023). "Further, the higher levels of circulating leptin can also incur cardiac hypertrophy and endothelial dysfunction." (PMID 37941902, 2023). "Endothelial dysfunction can be promoted by leptin, FT4, insulin and CRP while adiponectin improves endothelial dysfunction by inducing the production of nitric oxide." (PMID 36520252, 2023). "Leptin plays a crucial role in metabolism, apoptosis, extracellular matrix remodeling, endothelial dysfunction, and thrombosis." (PMID 35186940, 2022). "Leptin, one of systemic adipokines increased in critically ill COVID-19 patients is known to promote endothelial dysfunction and coagulation." (PMID 35837388, 2022). "This contributes to endothelial dysfunction and indicates the proatherogenic role of leptin in hyperleptinemia." (PMID 36579566, 2022). "Studies of CKD patients and in vitro data on human umbilical vein endothelial cells indicate that the higher leptin concentrations promote endothelial dysfunction in CKD." (PMID 36289903, 2022). "In this age group (6–9 years), we found a significant association both between ALT and BChE with markers of inflammation, endothelial dysfunction, and IR, in turn resulting in a positive correlation between liver enzymes and leptin concentration." (PMID 33665176, 2021). "Previous work by our group demonstrated that reduced leptin levels and endothelial leptin signaling lead to endothelial dysfunction in gBscl2-/- mice, which is reversed by leptin supplementation." (PMID 34638939, 2021).
endothelial dysfunction (continued). "Accumulating evidence from both in vivo and in vitro studies link circulating leptin levels with endothelial dysfunction (ED)." (PMID 33925217, 2021). "We demonstrated, for the first time to our knowledge, that HIV protein Tat plays a critical role in the viral infection-induced endothelial dysfunction via elevation of Nox1 expression and reduction in adipokine leptin secretion." (PMID 34681637, 2021). "Leptin and visfatin, which are involved in regulating endothelial function and NO-dependent vasorelaxation, have been proposed as clinical markers of endothelial dysfunction and vascular injury in cardiovascular diseases." (PMID 34422210, 2021). "Proposed pathways underlying this association include activation of the rennin-angiotensin-aldosterone system and increased procoagulatory activity, insulin resistance, sympathetic activity, leptin resistance, and endothelial dysfunction." (PMID 32172619, 2020). "This contributes to endothelial dysfunction and suggests a pro-atherogenic role of leptin under situations of hyperleptinemia." (PMID 33081064, 2020). "In female mice, leptin was found to induce endothelial dysfunction through aldosterone-dependent mechanisms." (PMID 33391033, 2020). "On the one hand, leptin in animal models demonstrated proinflammatory activity, which was associated with remodeling of ECM, WAT inflammation, endothelial dysfunction." (PMID 33240938, 2020). "Due to the proinflammatory and prooxidant properties of leptin, hyperleptinemia produces systemic endothelial dysfunction." (PMID 33076921, 2020). "Regarding the endothelium, several studies have suggested that leptin contributes to endothelial dysfunction." (PMID 33081064, 2020). "This study was limited to compare the factors related to endothelial dysfunction or cardiac anatomic findings with the serum leptin, or adiponectin levels and/or the serum L/A ratio." (PMID 33148166, 2020). "They demonstrated that the genetic ablation of leptin or its receptor aggravated the endothelial dysfunction and dampened the vascular reactivity of BK." (PMID 33316969, 2020). "Obesity leads to a dysfunction of PVAT which releases elevated levels of pro-inflammatory factors adipokines such as leptin, cytokines and chemokines directly to the vascular wall, contributing to endothelial dysfunction and inflammation." (PMID 31330870, 2019). "Visceral AT can induce leptin and insulin resistance, which increase both systemic vasoconstriction and endothelial dysfunction." (PMID 31330870, 2019). "There is evidence that PVAT potentiates leptin-induced endothelial dysfunction and increases vasomotor tone in coronary arteries of Ossabaw swine." (PMID 29523165, 2018). "The generation of ROS by leptin reduces the bioavailability of nitric oxide (NO) in VSMCs by inactivating NO or eNOS and leads to endothelial dysfunction." (PMID 25573199, 2015). "In this review, we discuss the diverse roles of leptin and adiponectin in endothelial dysfunction with emphasis on proangiogenic/proatherogenic factors in the endothelial cells." (PMID 25650072, 2015). "This study aimed to evaluate serum levels of Hcy and leptin, which have been proposed to contribute to the endothelial dysfunction and uveal inflammation that occur in both BU and NBU patients." (PMID 27800222, 2015). "At this point, the results obtained reflected only a direct correlation of leptin, levels of miR21 and sinusoidal endothelial dysfunction." (PMID 25658689, 2015). "IH applied to HFD mice induced a major increase in insulin and leptin levels and prevented endothelial dysfunction by restoring NO production." (PMID 25993257, 2015). "As mentioned, leptin has been shown to induce oxidative stress by increasing the formation of reactive oxygen species (ROS), a key mediator of endothelial dysfunction." (PMID 25650072, 2015).
endothelial dysfunction (continued). "In this review, we focus on two of the most abundant circulating adipokines, that is, leptin and adiponectin, in the development of endothelial dysfunction." (PMID 25650072, 2015). "In addition, leptin promotes the production of proliferative and inflammatory cytokines, it increases platelet aggregation and enhances the secretion of pro-atherogenic lipoprotein lipase by cultured human and rodent macrophages causing endothelial dysfunction by increasing ROS." (PMID 25573199, 2015). "In Ossabaw swine with metabolic syndrome, epicardial PVAT-derived leptin enhancement aggravates endothelial dysfunction via a PKC-β-dependent pathway." (PMID 24307898, 2013). "Possibly, the most relevant aspect of this theory is that leptin concentrations actually existing in obese patients do elicit endothelial dysfunction." (PMID 23573411, 2013). "Other candidate biological pathways that may be responsible for these associations include pro-coagulant factors, sympathetic activation, endothelial dysfunction, and adipocytokines, such as leptin, this ultimately leads to CVD." (PMID 40438360, 2025). "Also, data from preclinical studies indicate that adipocyte-derived leptin induces endothelial dysfunction, whereas endothelium-derived leptin has protective effects on it, with significant differences in males and females." (PMID 40002792, 2025). "Experimental data and clinical studies in CKD indicate that leptin in high concentrations can produce endothelial dysfunction by modifying the f-actin cytoskeleton through a mechanism involving the protein kinase B/glycogen synthase kinase β (AKT/GSK3β), nitric oxide, and β-catenin pathway." (PMID 39062887, 2024). "High levels of leptin may induce the synthesis of endothelin-1 which leads to endothelial dysfunction." (PMID 37872379, 2024). "We did not record associations of serum leptin with endothelial dysfunction, but we followed only FMD and not molecules such as vascular cell adhesion protein 1 (V-CAM 1) and intercellular adhesion molecule 1 (I-CAM 1), as in other studies." (PMID 39062887, 2024). "Additionally, adiponectin, which plays a protective role against endothelial dysfunction and arteriosclerosis, was decreased, and inflammatory adipokines, such as leptin and TNF-α, were increased in the HFHSD-only groups." (PMID 37047458, 2023). "For example, future work would examine nitrates/nitrites or citrulline, nitric oxide synthase metabolites, adiponectin, resistin, or leptin concentrations so as to confirm the herein revealed endothelial dysfunction, especially if correlated to hormones levels." (PMID 35327688, 2022). "Second, visceral adipose tissue accumulation could promote changes in adipokines (leptin and adiponectin) expression, another factor contributing to inflammation and endothelial dysfunction." (PMID 36320060, 2022). "The decreased adiponectin and the increased leptin and inflammatory cytokines may also lead to endothelial dysfunction." (PMID 35955653, 2022). "The effect of leptin on endothelial dysfunction might contribute to DVT of lower extremities and pulmonary embolism." (PMID 35186940, 2022). "Leptin may contribute to the development of cardiovascular dysfunction by inducing inflammation, oxidative stress and endothelial dysfunction." (PMID 33925217, 2021). "To investigate the impact of reduced fat mass and leptin levels on the vascular function, we assessed whether restoration of leptin levels via chronic infusion restores Tat-induced endothelial dysfunction." (PMID 34681637, 2021). "In contrast, we previously reported that mice with congenital generalized lipodystrophy (CGL) and mice treated with HIV protease inhibitor ritonavir exhibit endothelial dysfunction due to reduced leptin secretion, and leptin supplementation strikingly restored endothelial function." (PMID 34681637, 2021).
endothelial dysfunction (continued). "The overlap between leptin and FMD, especially as it relates to cardiovascular-related functional pathways, supports the substantial, potentially direct role that leptin may play in endothelial dysfunction and subsequent cardiometabolic pathology." (PMID 31466225, 2019). "Also, adipose tissue function markers such as leptin, adiponectin and interleukin-6 have been reported to change after SGLT2i treatment and to interplay on mediation of endothelial dysfunction." (PMID 31384310, 2019). "Moreover, increased secretion of adipokines such as proinflammatory cytokines like TNFα, IL-6 and leptin can result in endothelial dysfunction, with the possible involvement of the of kidney vasculature." (PMID 30016369, 2018). "Though several studies have been carried out in recent years for finding plausible mechanisms for NASH causation and treatment, the role of oxidative stress, adipokine leptin and its effect on sinusoidal endothelial dysfunction and NASH progression has been unclear." (PMID 25658689, 2015). "Previous reports showed that smoking-related damage via low grade inflammation and endothelial dysfunction may persist after smoking cessation and continue to influence leptin and adiponectin levels." (PMID 26869871, 2015). "Measurements of proinflammatory cytokines and oxidative stress in obese children revealed many markers that might contribute to endothelial dysfunction such as higher levels of leptin, resistin, and IL-6 as well as lower levels of adiponectin." (PMID 26011530, 2015). "Leptin, adiponectin, monocyte chemoattractant protein- (MCP-) 1, plasminogen activator inhibitor- (PAI-) 1, tumour necrosis factor (TNF) α, interleukin- (IL-) 6, and resistin are a few of these adipokines implicated in endothelial dysfunction." (PMID 25650072, 2015). "More importantly, hyperleptinemia induced endothelial dysfunction may play a crucial role in the differential actions of leptin." (PMID 25650072, 2015). "Leptin, IL-6, and CRP via deduction of nitrite oxide affect the endothelial activities and this process causes vascular contraction, leucocytic adherence, platelets activation, oxidative stress, and thrombosis that will result in endothelial dysfunction." (PMID 25242867, 2014). "In addition to raised serum leptin level, generalised endothelial dysfunction is evidently also present in women with pre-eclampsia." (PMID 24167814, 2013). "Taken together, these findings suggest that stress-induced leptin may partially contribute to the development of endothelial dysfunction." (PMID 24223557, 2013). "Different mechanisms support these associations; for example, IR provokes low-grade inflammation, endothelial dysfunction, and arterial stiffness and, also by the interaction with leptin, may activate the sympathetic nervous system and alter renal sodium handling." (PMID 38482609, 2025). "Mechanisms of this association include activation of the renin-angiotensin-aldosterone system by increasing sympathetic activity, insulin resistance, leptin resistance, increased procoagulant activity, and endothelial dysfunction, which may lead to HTN and cardiovascular disease." (PMID 38566160, 2024). "Several interrelatedfunctional changes, such as inflammation, endothelial dysfunction,leptin dysfunction, and gastric hunger hormone regulation, may lead toincreased sympathetic neural activity, decreased cardiac stress reflexsensitivity, and promote CAN development." (PMID 39139439, 2024). "Leptin is involved in several types of cellular dysfunction, such as proinflammatory processes, oxidative stress, angiogenesis enhancement, atherogenesis and thrombotic events, and endothelial dysfunction improvement as well as arterial tightness and atherosclerotic plaque development." (PMID 37238961, 2023).
endothelial dysfunction (continued). "Together, our in vitro findings suggest that altered systemic leptin or other plasma adipokine levels might not be driving endothelial dysfunction associated with the severe organ manifestations in obese COVID-19 patients admitted to the ICU." (PMID 35837388, 2022). "Since elevated leptin has a role in endothelial dysfunction, proinflammatory and profibrotic action in mediating NASH progression, it will be important to see whether it can regulate these pathways through epigenetic modulation, especially by up regulating microRNAs." (PMID 25658689, 2015). "Thus, an increase in the leptin level in the placenta maybe a compensatory mechanism directed against endothelial dysfunction, which isobserved in PE." (PMID 25093114, 2014). "Some previous studies in nonpregnant animals have also linked leptin to induction of endothelial dysfunction secondary to oxidative stress, decreases in paraoxonase activity, platelet aggregation, migration, hypertrophy, and proliferation of vascular smooth muscle cells." (PMID 24167814, 2013). "Therefore, it is tempting to speculate that IP-10 might play a connecting role between elevated circulating leptin levels and the generalized endothelial dysfunction characteristic of preeclampsia." (PMID 21906313, 2011). "Leptin may also promote endothelial dysfunction, though this remains controversial." (PMID 20066136, 2008). "In vitro, studies have found that leptin increases vascular endothelial growth factor (VEGF) synthesis, a marker of endothelial dysfunction." (PMID 38541144, 2024). "In concert with our previous work, we demonstrated that chronic leptin administration was able to restore endothelial function, indicating the regulatory role of leptin signaling in the HIV viral Tat protein-induced endothelial dysfunction." (PMID 34681637, 2021). "Obese children, in general, have higher concentrations of leptin and CRP and are vulnerable for endothelial dysfunction." (PMID 31466225, 2019). "Leptin and adiponectin are adipose tissue-based cytokines whose levels are altered in endothelial dysfunction and which are thought to be involved in CVD aetiology; increases in adiponectin are protective and in leptin are damaging to vascular homeostasis." (PMID 29180005, 2018). "However, other mechanisms by which leptin may contribute to vascular damage—such as inflammation, oxidative stress, endothelial dysfunction, as well as increased sympathetic tone—are preserved in obese subjects and can contribute to pro-thrombotic action of leptin." (PMID 20652043, 2010). "Leptin, however, induces mitochondrial superoxide production and MCP1 (monocyte chemotactic protein 1) expression in endothelial cells, endothelial dysfunction and CRP (C-reactive protein) expression." (PMID 19689798, 2009). "This, in turn, leads to a dysregulated release of inflammatory cytokines and adipocytokines, including leptin, lipocalin, and TGF-beta, which contributes to the development of oxidative stress, inflammatory response, endothelial dysfunction, and microvascular remodeling." (PMID 37441866, 2023). "We therefore hypothesized that adipokines such as leptin may prime endothelial cells, thereby facilitating SARS-CoV-2 sensing and/or infection and driving the endothelial dysfunction which is characteristic of severe COVID-19." (PMID 35837388, 2022). "Our current study furthers this narrative by showing that early changes in leptin transcription in PVAT are concurrent with dynamic alterations in vascular reactivity albeit not endothelial dysfunction per se." (PMID 34327871, 2021). "The authors attributed the lack of statistical reduction in endothelial dysfunction markers as adiponectin, leptin, ICAM, and VCAM due to methodological analysis limitations." (PMID 34012421, 2021).